RNF213 (ring finger protein 213)
Diseases named in the same sentence as RNF213 in open-access papers (continued):
Sharing a sentence is not in itself a finding about the gene and the disease.
vasculopathy (24 papers, 2017 to 2025). "The term “RNF213-associated vasculopathy” has been proposed to encompass the broader vascular spectrum linked to these mutations." (PMID 41001206, 2025). "RNF213 mutations, especially the R4810K variant that is predominant in east Asian populations, have also recently been associated with other vasculopathies, including pulmonary, coronary, and renal." (PMID 40497951, 2025). "Although the roles of the RNF213 gene in vascular anomalies are poorly understood, the associations of different variants with different kinds of vascular disorders have been established, especially in Asian patients." (PMID 40259928, 2025). "This broader understanding suggests that MMV represents a central nervous system-specific phenotype within the spectrum of RNF213-associated vasculopathy." (PMID 41001206, 2025). "Although the connection between RNF213 mutations and vascular disorders has been highlighted, recent research suggests that the ubiquitination activity of RNF213 plays an essential role in host defense against microbial infections." (PMID 37655297, 2023). "There is growing evidence that RNF213 and its mutants are linked to vasculopathy with a range of clinical presentations that include MMD as well as other intracranial and systemic vasculopathies." (PMID 37655297, 2023). "As we deepen our understanding of how the RNF213 gene mutation precipitates vasculopathy, we foresee a surge in research efforts aimed at predicting the presentation of vasculopathy and exploring gene therapy interventions." (PMID 38115307, 2023). "Our study highlights the unique presentation of the RNF213 p.R4810K variant, revealing manifestations of diverse forms of vasculopathy within a single-family lineage." (PMID 38115307, 2023). "In summary, several vasculopathies in different organs linked with RNF213 variants can be integrated and organized within the concept of “RNF213-associated vascular disease”." (PMID 35455046, 2022). "If gross vascular morphological characteristics related with the RNF213 c.14429G > A mutation can be demonstrated, various angiogenic or vasculopathy properties of MMD can be understood as a gross phenomenon." (PMID 31197213, 2019). "Finally, the role of epigenetic factors in the expression of both genes and their association should be considered, particularly in the occurrence of RNF213-associated vasculopathies." (PMID 40869930, 2025). "Over time, the concept of RNF213-associated vasculopathy has evolved." (PMID 40869930, 2025). "Therefore, we aimed to present a case detailing vasculopathy manifesting in diverse forms within a family carrying the RNF213 p.R4810K variant." (PMID 38115307, 2023). "Although RNF213 variants have been associated with various vascular disorders, the mechanisms through which they contribute to these disorders are unknown." (PMID 32182997, 2020). "Furthermore, the expression of both RNF213 and Cav-1 in endothelial cells, the primary cell type implicated in RNF213-related vasculopathies, further implies that their interaction may be of biological significance." (PMID 40497951, 2025). "However, this inconsistency may be explained by the different stages of RNF213-related vasculopathy between variant carriers with advanced MMD and those with sporadic ischemic stroke or TIA in our cohort, which excluded MMD." (PMID 34335228, 2021). "An additional atypical case was reported, a case of RNF213-related vasculopathy presenting with hemichorea, which suggested the impairment of angiogenesis and basal ganglia circuitry, leading to chorea-like symptoms." (PMID 40869185, 2025). "Clearly, a deeper understanding of such relationships and pathways will be crucial for developing targeted interventions that can restore endothelial cell function and improve outcomes for patients with RNF213-related vasculopathies." (PMID 40497951, 2025).
vasculopathy (continued). "Accumulating evidence suggests a continuum between MMD and a subset of large artery atherosclerosis, now conceptualized as RNF213-related vasculopathy." (PMID 39858606, 2025). "These phenotypes reflect the systemic nature of RNF213-related vasculopathy beyond the cerebral vasculature." (PMID 40869987, 2025). "This expanded view of RNF213-related vasculopathy underscores its role as a unifying concept in systemic vascular diseases, suggesting a common genetic basis for various vascular pathologies." (PMID 39858606, 2025). "Further studies are warranted to comprehend and define the novel disease spectrum of RNF213‐related vasculopathy in the East Asian population." (PMID 41582976, 2022). "That is, patients with advanced MMD, who represent the extreme end of the disease spectrum of RNF213-related vasculopathy, have terminal ICA stenosis or occlusion." (PMID 34335228, 2021). "Both the continuity and differences between MMD and non-moyamoya ischemic stroke in the same variant carriers should be further clarified to establish and stratify treatment strategies for RNF213-related vasculopathy." (PMID 34335228, 2021). "Currently, the exact biochemical and pathologic roles of RNF213 in vascular disorders remain controversial." (PMID 32182997, 2020). "A relevant issue is provided by the Asian prevalence of RNF213 variants and related vasculopathy, the association in non-Asian populations being weaker but also less studied outside definite diseases (e.g., moyamoya arteriopathy)." (PMID 40869930, 2025). "As a first step in determining the possible interactions between RNF213 and Cav-1, we analyzed their subcellular localizations in endothelial cells, which express both RNF213 and Cav-1, and which are considered as the primary targets of RNF213-related vasculopathies." (PMID 40497951, 2025). "Recent studies have expanded the scope of RNF213-related vasculopathy beyond MMD." (PMID 39858606, 2025). "The RNF213 Arg4810Lys variant consistently impacts angiogenesis, leading to vasculopathy characterized by the negative remodeling of both intracranial and systemic blood vessels." (PMID 40869185, 2025). "The discovery of the RNF213 p.R4810K variant has not only expanded our understanding of MMD but also revealed a broader disease spectrum, including isolated ICASO, recurrent IS, and subclinical vasculopathy." (PMID 40869987, 2025). "Second, why do some RNF213 heterozygotic variants never lead to the development of any vasculopathy?" (PMID 35455046, 2022). "In contrast, patients on the less severe end of the RNF213-related vasculopathy spectrum may still have activation of the mechanisms that compensate for insufficient anterior circulation through the PComAs, PCAs, and meningeal arteries." (PMID 34335228, 2021). "Here, we report the first case of hemichorea in RNF213-related vasculopathy." (PMID 33482763, 2021). "However, as RNF213-related vasculopathy does not meet the diagnostic criteria for MMD, the creation of a new disease category has been suggested." (PMID 33482763, 2021). "Specifically, all four patients with structural vasculopathy subtype had a monogenic etiology (4/4, 100%): KRIT1 for CCM, RNF213 for MD, ENG for HHT, and PKD1 for PKD." (PMID 36580209, 2023). "Since the cause-and-effect relationships between RNF213 variants and several vasculopathies have not been fully clarified, further studies are required to elucidate the underlying mechanisms and organ-specific factors that regulate the progression of RNF213-associated vascular disease." (PMID 35455046, 2022). "Here, we report the first case of hemichorea in a RNF213-related vasculopathy other than MMD, which may help define the clinical spectrum of RNF213-related vasculopathy." (PMID 33482763, 2021). "Although related vasculopathies are not well characterized in MMD patients, several findings point towards RNF213 having a greater involvement in vasculopathy beyond that of MMD." (PMID 39857601, 2024).
cancer (22 papers, 2015 to 2026). A tumor composed of atypical neoplastic, often pleomorphic cells that invade other tissues. "RNF213 is also important in tumor survival in hypoxic environments, and has been shown to be mutated in several cancer types." (PMID 34361002, 2021). "Lastly, the comparison between GBs with different levels of H3.3 expression did not reveal any potential association with relevant clinical markers, except for RNF213, for which mutations are linked to cerebrovascular pathologies and are unfavorable in other cancers." (PMID 34771425, 2021). "In addition, RNF213 mutation, which was employed as a monitoring marker for CC patients in our study, is currently little known about its function and role in cancer." (PMID 32718341, 2020). "Since RNF213 is highly expressed in cancer, its ubiquitination substrate should theoretically be low expressed in cancer." (PMID 39125654, 2024). "The second most mutated gene (early-stage 16%; late-stage 6%) shared among our cancer samples was RNF213." (PMID 37446001, 2023). "The contribution of SLC26A11 to cancer development is exhibited when a chimeric protein forms by the fusion of RNF213 and SLC26A11 in CML." (PMID 37511575, 2023). "From these data, we selected potential biomarkers of cancer including six upregulated proteins (RNF213, CTSG, PGLYRP1, RPL8, S100A8, S100A9) and two downregulated proteins (GPX1, TNS1)." (PMID 34361002, 2021). "Mutations in MAATP53, EGFR, FAT4, KMT2C, ARID1A, FAT1, and RNF213 were observed in the original cancer tissues, whereas KRAS and BRAF mutations were not identified." (PMID 35721089, 2022). "Six of these proteins had a higher abundance in cancer patients than in healthy controls (RNF213/ring finger protein 213; CTSG/cathepsin G; PGLYRP1/peptidoglycan recognition protein 1; RPL8/ribosomal protein L8; S100A8/S100 calcium binding protein A8; S100A9/S100 calcium binding protein A9)." (PMID 34361002, 2021). "felis infection included the ring finger protein 213 (Rnf213) and Furin, which have been reported to be involved in angiogenesis and cancer progression, respectively indicating their role in advanced stages of cancer progression." (PMID 28201999, 2017). "Also, given the active angiogenesis in malignant tissues and inhibitory effects of some MMPs on cancer proliferation, RNF213 could be considered as a target molecule for future cancer treatments." (PMID 26278786, 2015). "In addition, RNF213 (an E3 ligase) ubiquitinated GDH1 and decreased its protein level, thereby restricting the nutrient absorption of cancer cells and acting as a tumor suppressor of cancer cells." (PMID 37190313, 2023). "Interestingly, three proteins of the proteins found in this study (RNF213, RPL8, GPX1) were also discovered as differentially expressed in a study in which platelet mRNA of cancer patients was compared to that of healthy individuals." (PMID 34361002, 2021). "However, the direct relationship between RNF213 and cancer has not been extensively explored." (PMID 39125654, 2024).
tumor (17 papers, 2017 to 2026). "Previous reports have indicated that RNF213 acts as a tumour suppressor and its mutation promotes tumour development and progression." (PMID 41344988, 2026). "A total of five apaQTL-SNPs (rs41301932, rs4494603, rs9890400, rs56066320, and rs41301932), located on RNF213, were significantly associated with LUAD risk (p < 0.05), and they inhibit tumor growth through ubiquitin-mediated degradation of ZBTB20." (PMID 39125654, 2024). "Bahn and colleagues in 2016 proposed RNF213 as a promoter of angiogenesis in an in vitro tumor model through the stabilization of the master angiogenesis regulator HIF-1 (hypoxia inducible factor 1)." (PMID 35562882, 2022). "Banh and colleagues, studying the tumor hypoxia microenvironment, stumbled onto RNF213." (PMID 35562882, 2022). "Prokineticin 2(PROK2)is an important contributor to tumor angiogenesis, Ring Finger Protein 213 (RNF213) is essential for normal vascular development, and Leucine Rich Alpha-2-Glycoprotein 1 (LRG1) plays a role in retinal vascularization abnormalities observed in oxygen-induced retinopathy." (PMID 36032067, 2022). "Our qRT‐PCR results revealed that the expression levels of TNFSF10 (p < 0.01), ECM1 (p < 0.01), and RNF213 (p < 0.01) were significantly increased in advanced LUAD tumor cells, whereas the expression of SCGB3A2 (p < 0.01), SCGB3A1 (p < 0.01), and SFTPC (p < 0.01) was increased in early LUAD." (PMID 33783985, 2021). "RNF213 has been reported to be a tumor suppressor in malignancy." (PMID 33200540, 2021). "Thus, RNF213 involvement in AS onset does not seem to strongly correlate with tumor localization." (PMID 38137511, 2023).
bacterial infection (6 papers, 2020 to 2025). "Here, we show that increased expression of Rnf213 is significantly regulated by interferon alpha/beta receptor (IFNAR) signaling during bacterial infection and ligand stimulation." (PMID 40623121, 2025). "This profound difference in bacterial load, particularly in the spleen, reveals a central role of RNF213 in the host defense against bacterial infection." (PMID 34599178, 2021). "However, the bacterial load in the spleen was comparable among these groups, suggesting that nonimmune cells but not immune cells are the dominant players in the process by which RNF213 suppresses bacterial infection in the brain." (PMID 40623121, 2025). "Subsequent RNF213 knockout experiments confirmed its role, as cells lacking RNF213 failed to ubiquitinate LPS upon bacterial infection." (PMID 40181599, 2025). "Our bone marrow transplantation experiments revealed the crucial role of RNF213 within nonimmune cells in maintaining the integrity of the BBB and preventing bacterial infection in the brain." (PMID 40623121, 2025).
genetic disorders (4 papers, 2020 to 2024). "The association of MA with genetic disorders, the high familial rate, and the strong linkage with variants of Ring Finger Protein 213 (RNF213)/Mysterin coding gene in East Asian patients strengthen the role of genetic factors in MA pathogenesis." (PMID 34948203, 2021). "Conversely, the association of MA with genetic disorders, the high familial rate, and the strong association with variants of Ring Finger Protein 213 (RNF213) gene in East Asian patients strengthen the role of genetic factors in MA pathogenesis." (PMID 32796702, 2020). "In addition, it is associated with some genetic disorders, as well as some variants of the RNF213 gene." (PMID 38790247, 2024).
infectious disease (2 papers, 2021 to 2025). A disorder directly resulting from the presence and activity of a microbial, viral, or parasitic agent in humans. "Our data reveal a previously unrecognized target by which RNF213 regulates the IFN-I response and establishes a link between this MMD susceptibility gene and infectious diseases." (PMID 40623121, 2025). "In summary, our data reveal a previously unrecognized target in the mechanism by which RNF213 regulates the IFN-I response and establish a link between this MMD susceptibility gene and infectious diseases." (PMID 40623121, 2025).
RNF213 also shares sentences with these, for which no sentence is quoted: hemorrhagic stroke (3 papers); cardiovascular diseases (2); chronic thromboembolic pulmonary hypertension (2); ovarian carcinoma (2); adenocarcinoma (1); angina pectoris (1); autism spectrum disorder (1); B-cell lymphomas (1); bile duct cancer (1); bipolar disorder (1); Cerebral Autosomal Dominant Arteriopathy with Subcortical Infarcts and Leukoencephalopathy (1); cerebral cavernous malformation (1); chronic kidney disease (1); connective tissue disorder (1); coronary artery stenosis (1); diabetic polyneuropathy (1); diabetic retinopathy (1); dyslipidaemia (1); esophagus carcinoma (1); familial hemiplegic migraine (1); fibromuscular dysplasia (1); follicular lymphoma (1); head and neck tumors (1); hearing loss (1); hemangioma (1); hepatocellular carcinoma (1); Hypercholesterolemia (1); hyperlipidaemia (1); immune disorder (1); inflammatory myofibroblastic tumor (1).
A further 28 diseases each share a sentence with RNF213 in 1 paper.